TTF1 (transcription termination factor 1)
Diseases named in the same sentence as TTF1 in open-access papers (continued):
Sharing a sentence is not in itself a finding about the gene and the disease.
cancer (147 papers, 2007 to 2026). A tumor composed of atypical neoplastic, often pleomorphic cells that invade other tissues. "This analysis revealed the strong expression of epithelial cell markers such as EpCAM and MUC-1 (approximately 70–60%), along with other cancer-associated markers, including TTF-1, Ki67, cytokeratin, and CD56." (PMID 39941799, 2025). "Genetic instability and the reprogramming of cancer cells may cause dedifferentiation and result in deregulation of TTF-1/NKX2-1." (PMID 36705380, 2023). "Interestingly, we also detected that the NKX2-1 encoding TTF1, the most specific marker for cancers originating from the lung, was downregulated in SQ, in line with recent knowledge of SQ immunomarkers." (PMID 25325012, 2014). "In AR-overexpressing NPC-B13 cells, AR appeared to regulate thyroid transcription factor-1 (TTF-1, encoded by NKX2-1 gene) and its downstream target epidermal growth factor receptor (EGFR), thereby promoting cancer cell proliferation." (PMID 41633021, 2026). "Results showed diffuse TTF-1/p40 co-expression in the cancer cells, which indicated that they exhibited differentiation of both glandular and squamous cells simultaneously." (PMID 39928773, 2025). "When contrasted with TG, an antibody to TTF-1 is a more sensitive marker for poorly differentiated carcinomas and metastasis." (PMID 40575170, 2025). "In this patient, positivity for napsin A was weak, while positivity for TTF-1 was strong, which suggests that the lung is the primary site of the cancer." (PMID 39292398, 2024). "Thyroid transcription factor 1 (TTF1) is an important cancer-related biomarker for clinical diagnosis, especially for carcinomas of lung and thyroid origin." (PMID 38276630, 2024). "Immunostaining with diagnostic markers such as cytokeratin 20 (CK20) and thyroid transcription factor 1 (TTF-1) can help differentiate these two cancers, but their sensitivity and specificity are limited." (PMID 38398178, 2024). "TTF1 immunopositivity has been used as a biomarker for the diagnosis of carcinomas of lung or thyroid origin by pathologists." (PMID 38276630, 2024). "In humans, a combination of immunohistochemical (IHC) markers, including thyroid transcription factor-1 (TTF-1), Napsin A, surfactant protein-A (SP-A), is used to diagnose carcinomas of pulmonary origin." (PMID 39902337, 2024). "When Napsin A was used instead of TTF1, the sensitivity further dropped to 78.4% for poorly differentiated carcinomas." (PMID 39584166, 2024). "In 71 out of 217 HCCs (32.71%), simultaneous positivity for VSIG1 and TTF-1 was seen, being more specific for G1/G2 carcinomas with a trabecular architecture and a longer OS (p = 0.004)." (PMID 38928294, 2024). "It is very uncommon that TTF-1 and P40 are expressed in the same cancer cells but in recent years some cases with TTF-1 and P40-positive NSCLC have been reported 43-46." (PMID 37324952, 2023). "Although TTF-1 had high sensitivity and specificity in this study and other studies, the definitive diagnosis of primary carcinoma sites in effusions requires a panel of immunohistochemical markers." (PMID 37675165, 2023). "TTF-1 expression was also found in small subsets of ovarian, endometrial, colorectal, and breast carcinomas." (PMID 33504059, 2021). "In contrast, the expression of irisin in the cancer stroma correlated weakly positively with p63 (r = 0.28, p < 0.0001) and weakly negatively with TTF-1 (r = −0.23, p < 0.0001)." (PMID 31614634, 2019). "Accordingly, TTF-1 is frequently used as a marker to distinguish carcinomas of pulmonary and thyroid origin." (PMID 30513627, 2018). "To verify this phenomenon, we also detected the expression of TTF-1 in these cancer cells, which also valuably reflected the intrinsic activity of TTF-1 promoter." (PMID 28325285, 2017). "Further markers for carcinomas as CEA, BerEP4 and TTF1 were used in the diagnostic process done before." (PMID 28358042, 2017).
cancer (continued). "For the here proposed system, ICC with cancer-specific markers (such as TTF-1 or BerEP4) as well as a mesothelial marker (such as calretinin) on cytospins at the tie of initial culture and after each splitting is recommended." (PMID 27548442, 2016). "The small cells carcinomas in addition often show positivity of TTF-1 (thyroid transcription factor-1) or less commonly CDX-2 (caudal homeobox 2 protein) in the GI tract." (PMID 25947008, 2015). "The expression of CK, EMA, CD117, SYN and TTF-1 in the present case indicated that the carcinoma was a neuroendocrine SCC." (PMID 25120705, 2014). "Although uncommonly, TTF-1 can also be expressed in carcinomas originating from other primary sites (e.g., colon)." (PMID 24716057, 2014). "TTF-1 is currently used in routine surgical pathology as an immunohischemical marker of primary carcinomas arising in thyroid and lung organs." (PMID 25238975, 2014). "TTF-1 is a very useful marker in distinguishing pulmonary adenocarcinomas from other primary carcinomas." (PMID 25274100, 2014). "For example, we profiled a case of poorly differentiated carcinoma metastatic to liver (CK+/CK7-/CK20-/TTF1-/p63+/SYN-/CD56-) who, after 6 cycles of carboplatin/paclitaxel had liver recurrence." (PMID 25415047, 2014). "In comparison, the tumors that expressed thyroid transcription 1 (TTF-1) nearly all the cancer cells were immunopositive." (PMID 24160469, 2013). "Immunohistochemical (IHC) analysis of 226 LUAD specimens showed that TTF-1-negative tumors were associated with epidermal growth factor receptor wild-type status, advanced stage, and worse progression-free and cancer-specific survivals." (PMID 40824335, 2025). "Data on the rate of TTF-1 expression in cancer are heterogeneous, however." (PMID 39377914, 2024). "Also in cancer, TTF-1 was shown to have high specificity for tumors derived from the lung and the thyroid." (PMID 39377914, 2024). "TTF-1/P40-positive hyperplasia and dysplasia (pre-cancer lesion) were found in all mouse lungs." (PMID 37324952, 2023). "Therefore, a combination of the positive and negative markers, including at least two mesothelial cell markers (D2-40, calretinin, WT1) and two cancer cell markers (TTF-1, CEA, polyclonal, claudin-4), is recommended for the diagnosis of DMPM." (PMID 36684194, 2022). "The first is a TTF-1 positive axillary lymph node that could be defined either as an unusual isolated differentiated cancer of unknown primary or as an even rarer case of ectopic lung epithelium which underwent malignant transformation." (PMID 33330521, 2020). "TTF‐1 has a prosurvival function in cancer cells via ROR1 induction and LMO3 oncogene regulation." (PMID 31782890, 2020). "As 80% of poorly differentiated carcinomas are positive for TTF-1, the authors suggest that the majority of them may derive from the peripheral alveolar epithelium of the TRU." (PMID 31935792, 2020). "For instance, TTF-1 immunostaining has been conventionally used as an important marker in patients with unknown primary cancer." (PMID 30999697, 2019). "IHC staining showed that PD-L1 positive cells were mainly TTF1-positive cancer cells." (PMID 30850589, 2019). "Ki-67, p63 and TTF-1 markers revealed nuclear expression in cancer cells." (PMID 30769852, 2019). "TTF-1 is enigmatic with dual roles in cancer cell survival and progression." (PMID 29079814, 2017). "Dysregulation and variants of TTF1 and TTF2 can cause many diseases, including cancers." (PMID 26356687, 2015). "Therefore, our study indicated that it was necessary to distinguish PMEC and MEC-like carcinoma by a combination with morphology, immunostains, such as TTF-1, and MAML2 rearrangement." (PMID 26575266, 2015).
cancer (continued). "Addressing TTF-1 could only confirm pulmonary origin of the carcinoma, although analysis of MAdL expression revealed the specific subtype." (PMID 21811254, 2011). "Lack of GFAP expression and nuclear positivity for TTF1 are common in embryonal components which may cause misinterpretation as carcinoma although these tumors do not express cytokeratins." (PMID 33876327, 2021). "A clinical cancer history, a more malignant cytological feature, such as brisk mitotic or apoptotic activities, positive epithelial immunoreactivities, and markers for possible metastatic origins, such as TTF-1 for pulmonary origin, are significantly conducive to the correct diagnosis." (PMID 31360694, 2019). "The dominant antigens on cancer cells were EpCAM, MUC-1, TTF-1, Ki67, cytokeratin, and CD56, whose average expression was around 70–60%." (PMID 39941799, 2025). "Immunophenotypically, the carcinoma was consistent with thyrocyte differentiation with expression of monoclonal PAX8, TTF1, and thyroglobulin (the last predominantly in extracellular colloid)." (PMID 34997561, 2022). "IHC revealed that the expression of TTF‐1 and ASCL1 showed positive correlation in the nucleus of cancer cells." (PMID 31782890, 2020). "On immunohistochemistry, the carcinoma cells were positive for cytokeratin 7 (CK7), CA 19-9, and EMA, and negative for CK20, α-fetoprotein, and thyroid transcription factor-1 (TTF-1)." (PMID 31432273, 2019). "We do not claim that the ubiquitous beta-arrestin-1 can replace the relatively lung-specific TTF1 or NAPSA21,23,24 for the identification of lung as the primary site of cancer." (PMID 30078843, 2018). "Slightly fewer proteins (10.8%) were uniquely bimodal only at the protein level, including important cancer-related proteins such as MEK1, mTOR, E2F1, TTF1, EIF4G, and JAB1." (PMID 29293502, 2018). "The identified downstream targets of miR-365 include cell division cycle 25A (CDC25A), cyclin D1 (CCND1), transcription termination factor 1 (TTF1), interleukin 6 (IL-6) and nuclear factor I B (NFIB) in various types of cancers." (PMID 28556798, 2017). "PD-L1 positivity was related to p40 expression (p = 0.013) and to TTF-1 and or Napsin expression (p = 0.039) in PSCGC carcinoma." (PMID 28671973, 2017). "The carcinomas are characterized with cytokeratin 7 (CK7), cytokeratin 20 (CK20), thyroid transcription factor 1 (TTF-1), estrogen receptor (ER) or prostate-specific antigen (PSA." (PMID 26695546, 2016). "Kaplan–Meier analysis showed that both recurrence-free survival (RFS) and cancer-specific survival (CSS) were significantly worse in TTF-1-negative cases." (PMID 40824335, 2025). "A key observation was reduced PD-L1 and PD-L2 expressions in TAMs from TTF-1-negative tumors, whereas no such difference was seen in cancer cells." (PMID 40824335, 2025). "Two patients with negative CD5 expression were positive for CK5/6 and p63 but negative for TTF-1, presented with typical carcinoma showing thymus-like differentiation of the thyroid gland morphologically." (PMID 41278290, 2025). "Both cancers were PDL1 < 0%, without any other actionable driver mutations, cytokeratin, CD56- and p40-positive, and TTF-1 negative." (PMID 39125735, 2024). "All of the NUT carcinomas were negative for TTF-1 (0%,) whereas five were weakly or diffusely positive for p40." (PMID 38326851, 2024). "Tumors were undifferentiated carcinomas, negative for most of the thyroid-specific markers (TTF1, TG), which instead revealed mouse normal thyroid tissue." (PMID 38744818, 2024). "PTH, GCM2, SYN, CgA, GATA3, and CAM5.2 are always positive in cancer cells, while TTF1, PAX8, CAL, and TG are always negative." (PMID 38019325, 2023).
cancer (continued). "TTF-1 and p40 IHC are also employed to distinguish ADC and SCC and duplex IHC for these two markers combined with mucicarmine special stain should re-enforce the carcinoma assignment on a single slide." (PMID 34963687, 2022). "We compared the dissemination at the main metastatic sites between TTF-1 positive and TTF-1 negative carcinomas; our results show a higher proportion of adrenal metastases in TTF-1 negative patients (p = 0.039)." (PMID 35885495, 2022). "Among TTF-1 negative carcinomas, the proportion of carcinomas with a profile other than CK7+/CK20- remains rare and concerns only 12.8% of cases in our series." (PMID 35885495, 2022). "The histology revealed a Not Otherwise Specified (NOS) carcinoma, TTF1 and P40 negative, TPS PD-L1 = 0%." (PMID 35621690, 2022). "Another limitation of our work is that we are interested in a particular subgroup concerning TTF-1 negative carcinomas." (PMID 35885495, 2022). "We compared the molecular profile used routinely between TTF-1 positive and TTF-1 negative carcinomas." (PMID 35885495, 2022). "On immunohistochemistry, the carcinoma cells were positive for CK 7 and negative for CK 20 and TTF-1." (PMID 31432273, 2019). "According to the results, staining for PDTC, TTF-1 and Tg was negative, and no differentiated cancer tissues were detected." (PMID 28726134, 2017). "Differential expression analysis between ER+ and ER– cancers identified over-expression of TTF1, LAF-4 and C-MYB (p ≤ 0.05), and between pCR vs non-pCRs, over-expression of CXCL9, AREG, B-MYB and under-expression of ABCG2." (PMID 28697743, 2017). "To identify the tissue origin of the carcinoma, we use cytokeratin 7 (CK7), cytokeratin 20 (CK20), thyroid transcription factor 1 (TTF-1), estrogen receptor (ER) in female patients or prostate-specific antigen (PSA) in male patients as the minimal set of markers." (PMID 26695546, 2016). "Notably, PD-L1 (programmed death-ligand 1) and PD-L2 expression in TAMs, but not in cancer cells, was significantly reduced in TTF-1-negative tumors." (PMID 40824335, 2025). "Finally, it seems that, among TTF-1 negative carcinomas, the proportion of rare carcinomas such as carcinomas muted for SMARCA4 would be more frequent." (PMID 35885495, 2022). "Moreover, the case described by Kosmas also showed negative staining for TTF-1 and napsin-A, which led the pathologists to suspect a malignant neoplasm of uncertain origin." (PMID 34071040, 2021). "Negative immunolabeling for TTF-1 and AFP excluded concurrent carcinomas of pulmonary and hepatic origin, respectively." (PMID 41321567, 2025). "Misinterpretation as carcinoma metastasis was common, since GFAP expression was absent in the primitive neuronal component, whereas TTF-1 expression was detected in 15/19 cases (79%) based on immunohistochemistry." (PMID 39899075, 2025). "Immunohistochemical analyses of the cancer cell line (passage number 23) also showed ALK expression (ALK-positive) and confirmed thyroidal origin (TTF1 positive, PAX8 positive, thyroglobulin negative)." (PMID 33878728, 2021). "Both males and females have a decline in the total malignant neoplasm and carcinoma not otherwise specified (NOS), also known as the “unspecified” group, in the mid 2000s as this was a time when immunostaining for TTF-1 was introduced by pathologists." (PMID 28580352, 2017). "After evaluating different commercially available antibodies to CK7, CK20, TTF-1, ER and PSA, we have identified antibodies, which work well in the appropriate positive and negative cancer cell types." (PMID 26695546, 2016). "The TTF-1 positivity and the absence of renal lesions on successive PET/CTs confirmed that our patient’s carcinoma originated in the thyroid, and not in the kidneys." (PMID 25254107, 2014). "Histological examination revealed a poorly differentiated carcinoma, AE1-AE3 and CK7 positive, CK20, TTF1 and OCT3-4 negative, with cytoplasmic vacuoles positive to anti-HCG antibody." (PMID 24034807, 2013).
cancer (continued). "Immunohistochemically, these carcinoma cells were negative for all three neuroendocrine markers, i.e., synaptophysin, chromogranin A and CD56, TTF-1, CEA, CK20, h-caldesmon, α-SMA, calponin, and CD10, but specifically positive for 34βE12, CK7 and p63." (PMID 23231806, 2012). "Furthermore, in keeping with other thyroid PSCC cases in the literature, a negative TTF-1 and thyroglobulin helps to support the diagnosis of PSCC by excluding a cancer arising from follicular thyroid cells." (PMID 24942336, 2014).
lung (8 papers, 2015 to 2024). "We analyzed ROR1 expression by quantitative real-time PCR (qRT-PCR) in 56 histologically confirmed lung AC, stage I to IV, in addition we evaluated its association with TTF-1 (thyroid transcription factor-1) expression and the main molecular alterations involved in lung cancerogenesis." (PMID 33172431, 2020). "In summary, this study provides the mechanistic insight on how TTF-1 increases cellular sensitivity to cisplatin, a chemotherapy commonly administered to lung AD patients." (PMID 31142791, 2019). "The only case in our dataset expressing TTF1 was a liver metastasis (ID-51)." (PMID 31537838, 2019). "Materials and methods: We compared the usefulness of six conventional (CK5/6, p40, p63, CK7, TTF1, and Napsin A) and three novel (PKP1, KRT15, and DSG3) markers to distinguish between lung SCC and AC in 85 small biopsy specimens (41 ACs and 44 SCCs)." (PMID 31809668, 2020).
gastrointestinal tumors (4 papers, 2009 to 2025). "Our study provides also data regarding the heterogeneity of TTF-1 and Napsin A expression in gastrointestinal tumors." (PMID 40564811, 2025). "The reason for the aberrant staining of the transcription factor TTF-1 in gastrointestinal tumors, however, has not yet been determined." (PMID 40564811, 2025). "Furthermore, TTF-1, PSA and CDx2 negative IHC excluded epididymal metastases from lung, thyroid, prostate and gastrointestinal tumors, respectively." (PMID 33912469, 2021).
infection (4 papers, 2012 to 2021). The state of being infected such as from the introduction of a foreign agent such as serum, vaccine, antigenic substance or organism. "Staining of PCLS for the presence of anti-TTF-1, which was identified as a marker for type II pneumocytes in sheep and swine, demonstrated that type II pneumocytes are susceptible to infection by BRSV-GFP." (PMID 24548739, 2014). "Ad5-CC10-Cre infection also resulted in LADC tumors, which were found exclusively in the alveolar space and displayed high expression of TTF1 and Sftpc as expected." (PMID 30642944, 2019). "MRNA of CCSP, SPC and TTF-1 (Clara and AT2 cells) were all significantly reduced during the course of infection, which is consistent with the data showing viral clearance of Clara and AT2 cells." (PMID 22355371, 2012).
Head and Neck Tumors (2 papers, 2023 to 2024). "The 4th edition of the World Health Organization Classification of Head and Neck Tumors (WHO-HNT) indicates that NPPA with positive expression of cytokeratin 19 (CK19) and TTF-1 and negative expression of TG is called TL-LGNPPA." (PMID 36705380, 2023).
inflammation (2 papers, 2018 to 2023). Aberrant reaction of the microcirculation characterized by movement of fluid and leukocytes from the blood into extravascular tissues. "Another study also reported that TTF-1 played a role in the regulation of pulmonary inflammation." (PMID 29950925, 2018).